FUNDC2 (FUN14 domain containing 2)
Description:
Binds directly and specifically 1,2-Diacyl-sn-glycero-3-phospho-(1'-myo-inositol-3',4',5'-bisphosphate) (PIP3) leading to the recruitment of PIP3 to mitochondria and may play a role in the regulation of the platelet activation via AKT/GSK3B/cGMP signaling pathways. May act as transcription factor that regulates SREBP1 (isoform SREBP-1C) expression in order to modulate triglyceride (TG) homeostasis in hepatocytes.
Synonyms: HCBP6; DC44; HCC3; PD03104
Tractability: Antibody: UniProt predicts a signal peptide or a membrane-spanning region. PROTAC: ubiquitination databases record sites on it; its protein half-life has been measured.
Gene: Protein-coding gene on chromosome X (155,025,980 to 155,060,304, forward strand). Ensembl gene ENSG00000165775.
Subcellular location: Mitochondrion outer membrane; Nucleus
Gene Ontology:
Molecular function: phosphatidylinositol-3,4,5-trisphosphate binding; protein binding
Biological process: intracellular triglyceride homeostasis; autophagy of mitochondrion; regulation of platelet activation
Cellular component: mitochondrial outer membrane; mitochondrion; nucleus
Homologues: Orthologues: chimpanzee FUNDC2 (99% identical), rabbit FUNDC2 (90% identical), pig FUNDC2 (83% identical), guinea pig FUNDC2 (75% identical), mouse Fundc2b (74% identical), mouse Fundc2 (74% identical), rat Fundc2b (65% identical), zebrafish fundc2 (48% identical), Caenorhabditis elegans fndc-1 (19% identical). Paralogues in human: FUNDC1 (46% identical).